CYP2B6 (cytochrome P450 family 2 subfamily B member 6)
Description:
A cytochrome P450 monooxygenase involved in the metabolism of endocannabinoids and steroids. Mechanistically, uses molecular oxygen inserting one oxygen atom into a substrate, and reducing the second into a water molecule, with two electrons provided by NADPH via cytochrome P450 reductase (NADPH--hemoprotein reductase). Catalyzes the epoxidation of double bonds of arachidonoylethanolamide (anandamide) to 8,9-, 11,12-, and 14,15-epoxyeicosatrienoic acid ethanolamides (EpETrE-EAs), potentially modulating endocannabinoid system signaling. Hydroxylates steroid hormones, including testosterone at C-16 and estrogens at C-2. Plays a role in the oxidative metabolism of xenobiotics, including plant lipids and drugs. Acts as a 1,4-cineole 2-exo-monooxygenase. Allele 2B6*9: Has low affinity for anandamide and can only produce 11,12 EpETrE-EAs.
Synonyms: CPB6; CYPIIB6; CYP2B; CYP2B7; EFVM; IIB1; P450
Tractability: Small molecule: a structure with a bound ligand is known; it belongs to a druggable protein family. Antibody: UniProt places it where antibodies can reach, with medium confidence. PROTAC: its protein half-life has been measured; a small molecule that binds it is known.
Target class: Cytochrome P450; Cytochrome P450 family 2B; Cytochrome P450 family 2; Enzyme; Cytochrome P450 2B6
Safety:
Unwanted effects reported when the protein is acted on. In parentheses: how it was acted on, where the effect was seen, and who reports it.
achieve a complete response (source: ClinPGx)
achieve a complete response but also drug toxicities (source: ClinPGx)
adverse events (eg. liver toxicity or CNS side effects) (source: ClinPGx)
better response to treatment with imatinib (source: ClinPGx)
cytogenetic resistance to imatinib (source: ClinPGx)
dose delay (source: ClinPGx)
drug toxicities (source: ClinPGx)
efavirenz-induced side effects, sleep- and central nervous system-related side effects (source: ClinPGx)
gastrointestinal toxicity (source: ClinPGx)
hemorrhagic cystitis (source: ClinPGx)
hepatotoxicity (source: ClinPGx)
leukopenia (source: ClinPGx)
liver injury (source: ClinPGx)
metabolism (source: ClinPGx)
metabolism of cyclophosphamide (source: ClinPGx)
nicotine dependence (source: ClinPGx)
no available evidence regarding any association (source: ClinPGx)
opioid dependence (source: ClinPGx)
oral mucositis (source: ClinPGx)
poorer response to treatment with imatinib (source: ClinPGx)
QT prolongation (source: ClinPGx)
require treatment for neonatal abstinence syndrome (source: ClinPGx)
severe cutaneous adverse events (source: ClinPGx)
side effects (source: ClinPGx)
SJS/TEN and DRESS Syndrome (source: ClinPGx)
Stevens-Johnson Syndrome/toxic epidermal necrolysis (source: ClinPGx)
Stevens-Johnson Syndrome/toxic epidermal necrolysis (SJS/TEN) (source: ClinPGx)
Stevens-Johnson Syndrome/Toxic Epidermal Necrolysis (SJS/TEN) or Drug Reaction with Eosinophilia and Systemic Symptoms (DRESS Syndrome) (source: ClinPGx)
veno-occlusive disease of the liver (source: ClinPGx)
Gene: Protein-coding gene on chromosome 19 (40,991,281 to 41,018,398, forward strand). Ensembl gene ENSG00000197408.
Subcellular location: Endoplasmic reticulum membrane; Microsome membrane
Subcellular location (Human Protein Atlas): Nuclear membrane; Cytosol; Nucleoplasm
Pathways (Reactome):
Metabolism: CYP2E1 reactions; Fatty acids; Phase I - Functionalization of compounds; Xenobiotics
Gene Ontology:
Molecular function: anandamide 11,12 epoxidase activity; anandamide 14,15 epoxidase activity; anandamide 8,9 epoxidase activity; estrogen 2-hydroxylase activity; heme binding; monooxygenase activity; testosterone 16-alpha-hydroxylase activity; testosterone 16-beta-hydroxylase activity; arachidonate epoxygenase activity; oxidoreductase activity, acting on paired donors, with incorporation or reduction of molecular oxygen, reduced flavin or flavoprotein as one donor, and incorporation of one atom of oxygen; iron ion binding; oxidoreductase activity, acting on paired donors, with incorporation or reduction of molecular oxygen
Biological process: ketone metabolic process; steroid metabolic process; xenobiotic catabolic process; xenobiotic metabolic process; epoxygenase P450 pathway
Cellular component: cytoplasm; endoplasmic reticulum membrane
Genetic constraint (gnomAD): Loss-of-function variants: 36 observed, 45.53 expected, observed/expected ratio (o/e) 0.79, 90% interval 0.61 to 1.04. The upper end of that interval is the gene's LOEUF score, 1.04, which puts it in group 4 of 6, group 1 being the genes least tolerant of losing a copy. Missense variants: 624 observed, 643.55 expected, observed/expected ratio (o/e) 0.97, 90% interval 0.91 to 1.04. Synonymous variants: 239 observed, 241.9 expected, observed/expected ratio (o/e) 0.99, 90% interval 0.89 to 1.1.
Homologues: Orthologues: chimpanzee CYP2B6 (99% identical), macaque CYP2B6 (91% identical), dog CYP2B6 (78% identical), pig CYP2B6B (78% identical), guinea pig CYP2B6 (66% identical), rabbit CYP2B4 (59% identical). Paralogues in human: CYP2A13 (52% identical), CYP2A7 (51% identical), CYP2A6 (51% identical), CYP2C8 (50% identical), CYP2S1 (49% identical), CYP2F1 (49% identical), CYP2C9 (48% identical), CYP2C19 (48% identical), CYP2C18 (47% identical), CYP2E1 (46% identical), CYP2J2 (41% identical), CYP2D6 (40% identical), and 3 more.
Diseases named in the same sentence as CYP2B6 in open-access papers:
CYP2B6 is named in the same sentence as 187 diseases in open-access papers, as found by Europe PMC text mining. Sharing a sentence is not in itself a finding about the gene and the disease. The quoted sentences say what the papers report.
malaria (54 papers, 2007 to 2025). Malaria is a serious and sometimes fatal disease caused by a parasite that commonly infects a certain type of mosquito which feeds on humans. "This study investigated the distribution of the CYP2B6*6 allele and P. falciparum clearance in symptomatic uncomplicated malaria patients prescribed artemether-lumefantrine." (PMID 40748991, 2025). "All patient groups had significant illness resolution, even though the parasite clearance varied amongst the malaria patients; some even had 0% parasitemia on day 3 despite having the variant CYP2B6*6 genotype." (PMID 40748991, 2025). "Another study amongst Nigerian HIV-malaria infected subjects explored the impact of CYP2B6 516GT polymorphism on NVR and artemether-lumefantrine drug-drug interaction." (PMID 34322158, 2021). "High frequency of the CYP2B6*6 allele is associated with poor clinical response in HIV/TB/Malaria patient cohort in Congo." (PMID 32858798, 2020). "Malaria patients in Adjumani district had a high frequency of the CYP2B6*6 variant allele." (PMID 40748991, 2025). "This study assessed the prevalence of the CYP2B6*6 genotype among patients with uncomplicated malaria treated with artemether-lumefantrine at Adjumani District Hospital in the West Nile region, Uganda." (PMID 40748991, 2025). "There is inadequate information on the implications of CYP2B6*6 variability on the efficacy of AL in malaria treatment in endemic settings." (PMID 40748991, 2025). "The frequencies of CYP2B6*6 genotypes in the malaria patients aligned with Hardy-Weinberg equilibrium (X2 = 0.9954, p = 0.6)." (PMID 40748991, 2025). "This study evaluated the distribution of CYP2B6*6 genotypes and the potential correlation with P. falciparum parasite clearance among malaria patients treated using AL at Adjumani District Hospital, Uganda." (PMID 40748991, 2025). "CYP2B6*6 variant and Efavirenz concentration impact on Lumefantrine plasma levels in HIV/Malaria patients in Tanzania." (PMID 32858798, 2020). "Identification of inter-individual variability for drug metabolism through cytochrome P450 2B6 (CYP2B6) enzyme is important for understanding the differences in clinical responses to malaria and HIV." (PMID 29559695, 2018). "So, a deeper knowledge of the genetic variability of CYP2B6 in the population of Botswana is necessary to improve the efficacy of ongoing fight against malaria and HIV." (PMID 29559695, 2018). "For this purpose, functional variant alleles in CYP450 (CYP2B6, CYP3A4, CYP3A5) and ABCB1 genes involved in the metabolism of anti-malarial drugs were assessed in pregnant malaria patients treated with ALu." (PMID 28673292, 2017). "For example the antiretroviral drug rilpivirine and a malaria drug were seen to inhibit CYP2B6 in vitro as well as the anti-platelet drug ticlopidine in vivo." (PMID 24885815, 2014). "High CYP2B6*6 interindividual variability is evident in malaria patients in Adjumani district." (PMID 40748991, 2025). "CYP2C8 along with CYP2B6, CYP3A4, and CYP3A5 metabolize drugs used in artemisinin-based combination therapy for malaria, and alleles such as CYP2C8*2, CYP2C8*3, CYP2B6*6, CYP3A4*1B, and CYP3A5*3 may affect patient response to this treatment." (PMID 36834793, 2023). "In addition, the drugs prescribed to treat cases of malaria are currently artemisinin-based combinations and these are metabolized by CYP2B6 genes." (PMID 34398016, 2021). "AIDS and malaria are common in Mali; therefore, establishing the genetic profile of CYP2B6 in our HIV patients infected with malaria parasite will facilitate better classification of patient according to their genotypes and alternative use of others antimalarials drugs." (PMID 34398016, 2021). "Another study in the malaria-endemic population of Timor Leste indicated that the prevalence of CYP2B6*4, *9, and *6 might impact the metabolism and efficacy of artemisinin and its derivatives among the Timorians." (PMID 34322158, 2021).
malaria (continued). "The high prevalence of the CYP2B6*6 allele means that artemether may not achieve optimal malaria parasite clearance." (PMID 40748991, 2025). "The possible influence of genetic variations in CYP2B6, CYP3A5 and ABCB1 on malaria treatment outcome was evaluated using Cox regression analysis." (PMID 28673292, 2017). "The relationship between the patient CYP2B6*6 genotype and parasite clearance in malaria patients has not been documented to highlight the effect of the genotype on parasite clearance." (PMID 40748991, 2025). "Results therefore show that pharmacogenetic variations in CYP2B6 and CYP3A5 influence plasma disposition of artemether and lumefantrine and likely affect malaria treatment outcome if medication is not adhered to." (PMID 38685044, 2024). "No significant influence of CYP2B6, CYP3A5 and ABCB1 c.4036A>Genotypes on malaria treatment outcome were observed." (PMID 28673292, 2017).
breast carcinoma (30 papers, 2004 to 2026). "Common genetic CYP2B6 variants (*4, *5, *6, *9) are associated with reduced enzymatic activity and have been linked to increased breast cancer risk and poor prognosis." (PMID 41636472, 2026). "In breast cancer patients receiving adjuvant chemotherapy with cyclophosphamide and doxorubicin, CYP2B6 rs3745274 (CYP2B6*9) was reported to be associated with a poor OS." (PMID 28178648, 2017). "Variant alleles in the ABCB1, SLC22A16 and CYP2B6 genes are associated with response to AC therapy in the treatment of breast cancer." (PMID 20179710, 2010). "Several CYP2B6 genotypes were associated with the metabolism of CYP2B6 substrate drugs, including cyclophosphamide and tamoxifen, frequently used in adjuvant therapy for breast cancer." (PMID 28178648, 2017). "Further research involving 230 breast cancer patients identified significant associations between CYP2C19 and CYP2B6 genotypes and OS." (PMID 39598531, 2024). "According to the prediction of clinical models, we found that CYP2B6 has a good prognostic value for the prognosis of breast cancer." (PMID 35350700, 2022). "ER binding sites were also observed in an upstream 5’ regulatory region of the CYP2B6 gene in several breast cancer cell lines." (PMID 33809117, 2021). "In pre-menopausal women with ER- and/or PR-positive breast cancer, SNPs in CYP2B6 such as CYP2B6 rs4802101 (T/T) and CYP2B6 rs3211371 (T/C) have been associated with adverse prognosis." (PMID 33809117, 2021). "In breast cancer, mRNA expression of CYP2B6 has been detected in both healthy and cancerous breast tissues." (PMID 33809117, 2021). "In Japanese breast cancer patients, those homozygous for CYP2B6*6 (Q172H and K262R) had higher clearance than heterozygous or homozygous for CYP2B6*1." (PMID 32390827, 2020). "Here, we studied the association of functionally significant variant alleles of CYP3A4, CYP3A5, CYP2B6, CYP2C8, CYP2C9 and CYP2C19 with the clinical response to neoadjuvant chemotherapy in breast cancer patients." (PMID 22702493, 2012). "We studied the association of the functionally significant variant alleles of CYP3A4, CYP3A5, CYP2B6, CYP2C8, CYP2C9 and CYP2C19 with the clinical response to neoadjuvant chemotherapy in breast cancer patients." (PMID 22702493, 2012). "For this purpose, we investigated the expression of CYP3A4, CYP2C9 and CYP2B6 in breast cancer tissue using Western Blotting." (PMID 14970873, 2004). "Additionally, multifactor dimensionality reduction (MDR) revealed significant gene-gene interactions between CYP2C19 and CYP2B6, influencing treatment responses in breast cancer patients." (PMID 39598531, 2024). "The association between certain CYP2B6 SNPs and the outcome of breast cancer patients receiving tamoxifen alone has not yet been reported." (PMID 28178648, 2017). "In the present study, we demonstrated that genetic variants of the host, such as SNPs of MAP3K1, CYP2B6, UGT1A1, HCN1, ABCB1, and ALDH3A1, may worse the prognosis of HR-positive breast cancer patients, predominantly for premenopausal women." (PMID 28178648, 2017). "Cyclophosphamide, the cornerstone of breast cancer chemotherapy in Ethiopia, is mainly metabolized to 4-hydroxy-cyclophosphamide by genetically polymorphic CYP3A, CYP2B6, CYP2C9, CYP2C19, and CYP2J2 enzymes." (PMID 31139078, 2019). "Functional analysis and validation of the biologic significances of SNPs of CYP2B6 rs3211371 and MAP3K1 rs889312 in this subtype of breast cancer patients are warranted." (PMID 28178648, 2017). "The ambiguous roles of CYP2B6 and CYP3A4 noted by this study warrant investigations focused on regulation of their expression and posttranscriptional processing specifically in breast carcinomas." (PMID 25526449, 2014). "Mechanisms of action of AKR1C2, AKR7A3, CYP2B6, CYP3A4, and CBR1 should continue to be further followed in breast carcinoma patients and models." (PMID 25526449, 2014). "CYP2B6 and CYP2C19 were previously reported as unfavorable prognosis markers in breast cancer." (PMID 34423049, 2021).
breast carcinoma (continued). "Germ line DNA samples from 230 patients with breast cancer on AC therapy were genotyped for the following SNPs: ABCB1 C1236T, G2677T/A and C3435T, SLC22A16 A146G, T312C, T755C and T1226C, CYP2B6*2, *8, *9, *3, *4 and *5, CYP2C9*2 and *3, CYP3A5*3 and CYP2C19*2." (PMID 20179710, 2010). "Moreover, an in vitro study has shown 17 β-estradiol to upregulate the expression of CYP2B6 exclusively in T-47D but not in MCF-7 breast cancer cells by increasing the recruitment of ER-α and nuclear receptor coactivator 3 (NCoA3) to the 5’ flanking region of the enzyme." (PMID 33809117, 2021). "Moreover, P450 GDEPT may be useful in treating a broad spectrum of cancers, including breast cancer, melanoma, pancreatic cancer, and metastatic liver cancer; 3) mammalian P450 subfamily 2B enzymes, in particular rat CYP2B1, human CYP2B6, and dog CYP2B11, are effective catalysts of CPA activation." (PMID 20836875, 2010).
AIDS (14 papers, 2006 to 2025). A syndrome resulting from the acquired deficiency of cellular immunity caused by the human immunodeficiency virus (HIV). "An AIDS Clinical Trials Group study reported an association between CYP2B6 516G>T SNP and neuropsychiatric symptoms within 1 week of efavirenz treatment, but not later, suggesting the development of tolerance to these adverse effects." (PMID 40182085, 2025). "Many previous pharmacogenomic studies in individuals with HIV/AIDS receiving EFV-containing treatment have reported that some patients have EFV plasma concentrations unexplained by the CYP2B6*6 and *18 variants." (PMID 31526233, 2019). "For example, in AIDS clinical studies, CYP2B6 variants have been associated with 2- to 4-fold higher plasma EFV and NVP in HIV patients; ≥2-fold higher plasma EFV concentration is associated with neuropsychological adverse effects." (PMID 23961363, 2012). "A Mozambican study found the frequency of CYP2B6 SNPs (516T/785G of (34.7% and 42.6%) and 516T associated to high NVP toxicity among HIV/AIDS patients." (PMID 35143515, 2022). "In this study, five herbal medicines commonly taken to treat and manage the effects of HIV/AIDS or its comorbidities by patients were evaluated for their ability to modulate activity of CYP2B6 in vitro using recombinant human CYPs." (PMID 26891286, 2016). "Several pharmacogenetics studies on HIV/AIDS cohorts on EFV-containing regimens have shown that the CYP2B6 c.516G>T SNP affects plasma EFV levels." (PMID 26402689, 2015). "In summary based on the current population pharmacokinetic analysis and simulation study, we propose CYP2B6 genotype based EFV dosage adjustment for HIV/AIDS patients in Uganda and the entire sub-Saharan Africa." (PMID 24497997, 2014). "Gender, weight, and CYP2B6 genotype influence Efavirenz HIV/AIDS and TB treatment in Zimbabwe." (PMID 32858798, 2020). "Since CYP2B6 is a major determinant of the clinical metabolism of the antiretroviral efavirenz, this focus likely reflects the increased prevalence of HIV/AIDS in Sub-Saharan Africa." (PMID 39540424, 2024).
Obesity (12 papers, 2014 to 2025). Accumulation of substantial excess body fat. "Human CYP2B6 is also inversely associated with obesity as humans with low expression are more likely to be obese." (PMID 36611876, 2022). "Interstingly, reduced human hepatic CYP2B6 activity is associated with obesity." (PMID 36520866, 2022). "Similarly, human CYP2B6 is the only human detoxification CYP associated with obesity; low liver CYP2B6 expression is associated with obesity." (PMID 35391786, 2022). "Overall, our data indicates that CYP2B6 is an anti-obesity enzyme, but probably to a lesser extent than murine Cyp2b’s." (PMID 36520866, 2022). "In conclusion, the data presented indicates CYP2B6 is an anti-obesity enzyme in humanized mice, which verifies epidemiological data." (PMID 36520866, 2022). "There are several potential mechanisms by which CYP2B6 could be an anti-obesity enzyme that provides protection against insulin resistance while increasing steatosis." (PMID 40002708, 2025). "However, humanized CYP2B6 transgenic (hCYP2B6-Tg) mice are sensitive to diet-induced hepatic steatosis despite their resistance to obesity." (PMID 40002708, 2025). "Therefore, the inhibition of CYP2B6 by xenobiotics or dietary fats can exacerbate obesity and metabolic disease potentially through disrupted PUFA metabolism and the production of key lipid metabolites." (PMID 36520866, 2022). "In addition, several of the CYP2B6-produced 9- and 13-position oxylipins are PPARα and PPARγ activators, providing a putative mechanism for CYP2B6 as an anti-obesity enzyme." (PMID 36520866, 2022). "Furthermore, carnosic acid which has been suggested as a potential treatment for obesity and nonalcoholic fatty liver disease has showed increased CYP2B6 enzyme activity thus indicating a potential drug interaction with carnosic acid." (PMID 24885815, 2014). "Furthermore, CYP2B6 is protective against diet-induced obesity in female transgenic mice expressing the human CYP2B6 gene (hCYP2B6-Tg), with males showing greater steatosis surprisingly coupled with greater glucose resistance, as measured with a glucose tolerance test." (PMID 40002708, 2025). "However, the role of CYP2B6 as an anti-obesity gene has not been assessed." (PMID 36520866, 2022).